GDF15 (growth differentiation factor 15)
Diseases named in the same sentence as GDF15 in open-access papers (continued):
Sharing a sentence is not in itself a finding about the gene and the disease.
arteriosclerosis (2 papers, 2021 to 2024). A vascular disorder characterized by thickening and hardening of the walls of the arteries. "GDF15 remained significantly associated with arteriosclerosis even after accounting for clinical factors such as age, gender, body mass index, systolic blood pressure, fasting blood glucose, smoking, and the apnea–hypoxia index (AHI)." (PMID 38378599, 2024). "Specifically, GDF15, a serum biomarker, significantly improved the diagnostic accuracy of Model 4 for arteriosclerosis in patients with OSA (Chi-square increased from 25 to 50)." (PMID 38378599, 2024). "This study verified the independent and incremental value of GDF15 in identifying arteriosclerosis in OSA patients, surpassing clinical risk factors and other serum biomarkers such as AOPP and IL-6." (PMID 38378599, 2024). "Among these, GDF15 exhibited an independent association with arteriosclerosis even after adjusting for age, gender, body mass index, SBP, FBG, smoking, AHI, AOPP, and IL-6 in Model 5 (OR [95%CI] = 1.46 (1.21–1.78); p < 0.03)." (PMID 38378599, 2024). "GDF15 demonstrated the largest area under the curve (AUC) for identifying arteriosclerosis in OSA patients (AUC, 0.85 [0.77–0.94])." (PMID 38378599, 2024). "The results revealed that AHI, AOPP, IL-6, and GDF15 were significant predictors of arteriosclerosis." (PMID 38378599, 2024). "Previous researches had shown the connections between IL-6 and arteriosclerosis in an animal study, AOPP and arteriosclerosis in healthy individuals, and GDF15 and arteriosclerosis in the general population." (PMID 38378599, 2024). "This study is notably the first to investigate the incremental value of AOPP, IL-6, and GDF15 in detecting arteriosclerosis within the OSA population." (PMID 38378599, 2024). "Arterial stiffness increases with age, and we therefore hypothesized that GDF15 could serve as a biomarker of arteriosclerosis in patients with OSA." (PMID 38378599, 2024). "Notably, the combination of AHI and GDF15 demonstrated the highest incremental AUC of 0.86 (95% CI [0.78–0.94]) for accurately identifying arteriosclerosis." (PMID 38378599, 2024). "Secondly, GDF15 emerged as an independent predictor of arteriosclerosis in patients with OSA." (PMID 38378599, 2024). "The objective of this study was to determine the independent and incremental values of advanced oxidative protein product (AOPP), interleukin 6 (IL-6), and growth differentiation factor 15 (GDF15) in identifying arteriosclerosis in patients with obstructive sleep apnea (OSA)." (PMID 38378599, 2024). "Therefore, we used sequential nested models by adding AHI, AOPP, IL-6 and GDF15 sequentially for predicting arteriosclerosis in OSA patients." (PMID 38378599, 2024). "Additionally, GDF15 exhibited greater incremental value compared to AOPP or IL-6 in the detection of arteriosclerosis in patients with OSA." (PMID 38378599, 2024). "Additionally, in patients with OSA, the combination of AHI, AOPP, IL-6, and GDF15 yielded the highest AUC (0.87 [0.79–0.95]), demonstrating a sensitivity of 92.9% and specificity of 77.6% in identifying arteriosclerosis." (PMID 38378599, 2024). "In conclusion, GDF15 proved to be a valuable predictor of arteriosclerosis in patients with OSA." (PMID 38378599, 2024). "Consequently, GDF15 may improve the estimation of the pretest probability of arteriosclerosis and present new targets for diagnosing and treating OSA-associated arteriosclerosis, further reducing CVD morbidity and mortality in individuals with OSA." (PMID 38378599, 2024). "We could not find any associations between GDF-15 and arteriosclerosis, determined as medial calcification in epigastric artery biopsies." (PMID 34526107, 2021). "Firstly, AOPP, IL-6, and GDF15 levels were observed to be elevated in patients with OSA and arteriosclerosis in comparison to those with OSA alone." (PMID 38378599, 2024).
arteriosclerosis (continued). "Thirdly, GDF15 exhibited incremental value when compared to AOPP and IL-6 in the identification of arteriosclerosis among patients with OSA." (PMID 38378599, 2024). "The results showed that AOPP, IL-6, and GDF15 are all positively correlated with AHI and PWV_ES, which illustrated that the serum biomarkers are not only related to OSA but also to arteriosclerosis." (PMID 38378599, 2024). "In this investigation, the levels of serum biomarkers AOPP, IL-6, and GDF15 were found to be higher in individuals with OSA and arteriosclerosis compared to those with OSA only." (PMID 38378599, 2024). "Moreover, a comprehensive evaluation of clinical risk factors, including age, gender, body mass index, SBP, FBG, and smoking, along with serum biomarkers like AOPP, IL-6, and GDF15, may have a more profound impact on assessing arteriosclerosis in patients with OSA." (PMID 38378599, 2024). "Herein, the current study tried 1) to assess the predictive value of AOPP, IL-6, and GDF15 in relation to arteriosclerosis in patients with OSA; and 2) to examine the incremental value of AOPP, IL-6, and GDF15 in identifying arteriosclerosis in patients with OSA." (PMID 38378599, 2024). "We hypothesise that there are sex-specific relationships of GDF-15, YKL-40, MMP-9 with vascular outcomes (athero-/arteriosclerosis) and mortality in end-stage kidney disease (ESKD)." (PMID 34526107, 2021). "Compared to OSA patients without arteriosclerosis, those with arteriosclerosis exhibited significantly higher levels of AOPP, IL-6, and GDF15." (PMID 38378599, 2024). "Conversely, elevated levels of AOPP (58 vs. 56 μmol/L, p = 0.01), IL-6 (59 vs. 58 pg/mL, p = 0.03), and GDF15 (101 vs. 94 ng/mL, p = 0.01) were observed in the OSA patients with arteriosclerosis compared to those without arteriosclerosis." (PMID 38378599, 2024). "The results of our study also confirmed the predictive significance of GDF15 and provided evidence that GDF15 enhanced the ability to differentiate and reclassify patients with OSA more accurately, determining the presence or absence of arteriosclerosis." (PMID 38378599, 2024).
autoimmune hepatitis (2 papers, 2022 to 2025). Hepatitis caused by autoantibodies. "The same authors also demonstrated that remission of autoimmune hepatitis was associated with reduced GDF15 levels as well as positivity in the liver tissue." (PMID 41303556, 2025).
autoimmune thyroid disease (2 papers, 2017 to 2026). Inflammatory disease of the thyroid gland due to autoimmune responses leading to lymphocytic infiltration of the gland. "And we didn't find GDF-15 was associated with hypothyroidism and thyroid autoimmunity either." (PMID 28489602, 2017). "In patients with PAI, GDF15 showed positive correlations with disease duration and duration of autoimmune thyroid disease, gonadotropin levels, waist-to-hip ratio, and body fat percentage, and negative correlations with DHEAS and sex hormone levels." (PMID 41828483, 2026).
benign prostate hyperplasia (2 papers, 2022). "GDF-15 has recently been proposed as a potential marker to discriminate between PCa and benign prostate hyperplasia (BPH)." (PMID 36230513, 2022).
cardiogenic shock (2 papers, 2022 to 2023). "Although less studied, bacterial infections have also been associated with increased GDF-15 levels, both for Gram-positive or Gram-negative bacteria Similarly, GDF-15 was found to be elevated in patients with septic shock and its plasma levels were correlated with increased mortality." (PMID 35251002, 2022).
carditis (2 papers, 2023 to 2025). "Children with both newly diagnosed Kawasaki Disease (KD) and rheumatic fever had elevated GDF15 levels, but returned to normal after treatment, even in the setting of carditis." (PMID 40019842, 2025). "Also, there was a highly statistically significant difference in serum GDF-15 level among patients who had cardiac affection including; Echo abnormalities, presence of carditis, and low ejection fraction, compared to those who hadn’t." (PMID 37974205, 2023).
chronic hepatitis B (2 papers, 2020 to 2025). "As GDF-15 can reveal various pathological conditions, such as viral replication, inflammation, oxidative stress, hepatocyte apoptosis, and early fibrogenesis, it was found to be an excellent diagnostic biomarker for the detection of chronic hepatitis B in our study." (PMID 41157623, 2025). "In our study, GDF-15 was found to be “excellent” at distinguishing patients with chronic hepatitis B infection from healthy individuals, while CCL-20 was found to be “good”." (PMID 41157623, 2025). "In our current study, GDF-15 was found to be a superior biomarker for diagnosing chronic hepatitis B (AUC = 0.920, with 91.7% sensitivity and 83.3% specificity), outperforming many non-invasive markers." (PMID 41157623, 2025). "GDF-15 emerged as a robust and highly accurate marker for diagnosing chronic hepatitis B, while CCL-20 was found to be a dynamic indicator of inflammation induced by the virus." (PMID 41157623, 2025). "GDF-15 was found to be a good biomarker for distinguishing disease severity in patients with chronic hepatitis B. Quantitative GDF-15 values up to 509.515 indicate mild disease, 509.515–1051.161 indicate moderate disease, and 1051.61 and above indicate severe disease." (PMID 41157623, 2025). "Our study investigated four biomarkers, providing promising results that are more comprehensive and detailed for diagnosing and staging chronic hepatitis B. Each biomarker captures a different aspect of the disease: GDF-15 (stress/injury), CCL-20 (inflammation), and CXCL-16/CD8a (T cell dynamics)." (PMID 41157623, 2025). "This study has shown that the biomarkers GDF-15 and CCL-20 may be potential diagnostic biomarkers in detecting the presence of chronic hepatitis B, and the biomarkers CXCL-16, CCL-20, GDF-15, and CD8a may be potential diagnostic biomarkers in determining the severity of the disease." (PMID 41157623, 2025). "Our study has revealed valuable information that GDF-15, CCL-20, CXCL-16, and CD8a biomarkers, which can be measured quantitatively by a simple and cost-effective ELISA method, can be a tool that can support molecular testing (PCR) in the clinical management of chronic hepatitis B patients." (PMID 41157623, 2025).
clear cell renal cell carcinoma (2 papers, 2023 to 2025). "Contrary to this, a more recent paper showed that downregulation of GDF-15 in clear cell renal cell carcinoma suppresses ferroptosis." (PMID 38743322, 2025). "However, the role of GDF15 in clear cell renal cell carcinoma (ccRCC) remains poorly understood." (PMID 38082448, 2023). "We found that the expression level of GDF15 in tumor samples, compared to that in normal samples, was significantly decreased in kidney malignancies, including chromophobe renal cell carcinoma (KICH), clear-cell renal cell carcinoma (KIRC), and papillary renal cell carcinoma (KIRP)." (PMID 38082448, 2023).
colon adenoma (2 papers, 2015 to 2019). An adenoma that arises from the colon. "Our study systematically investigated the ability of GDF15 to induce hallmark behaviors of cancer in a variety of human colon adenoma and CRC cell lines and human colon organoids." (PMID 31389184, 2019). "This demonstrated that non-steroidal anti inflammatory drug (NSAID) users had a higher serum MIC-1/GDF15 level than non-users and only NSAID users with an elevated serum MIC-1/GDF15 level were protected from colonic adenoma recurrence." (PMID 25695521, 2015).
congenital adrenal hyperplasia (2 papers, 2020 to 2024). Congenital adrenal hyperplasia (CAH) is an inherited endocrine disorder caused by a steroidogenic enzyme deficiency that is characterized by adrenal insufficiency and variable degrees of hyper or hypo androgyny manifestations, depending of the type and the severity of the disease. "GDF15 levels were also significantly lower in patients with congenital adrenal hyperplasia after a 300-minute hydrocortisone infusion (hydrocortisone 547.0 pg/mL vs placebo 606.0 pg/mL)." (PMID 38795365, 2024).
coronary artery calcification (2 papers, 2021 to 2024). Calcification of the coronary artery, used as a measure of coronary atherosclerosis, a risk factor for myocardial infarction. "The association of GDF-15 and coronary artery calcification has already been evaluated in five other studies." (PMID 37548881, 2024). "To date, only a few studies have examined the impact of GDF-15 on coronary artery calcification, and the association between GDF-15 and ABI has not been evaluated." (PMID 37548881, 2024). "These compelling findings show that GDF-15 levels are associated with greater coronary artery calcification in males only, independent of age, comorbidities, glomerular filtration rate, and mortality." (PMID 34526107, 2021). "Increased GDF-15 correlated with higher TMAO in females only, and with higher coronary artery calcification and IL-6." (PMID 34526107, 2021).
dermatomyositis (2 papers, 2023 to 2025). Dermatomyositis (DM) is a type of idiopathic inflammatory myopathy characterized by evocative skin lesions and symmetrical proximal muscle weakness. "Similarly, GDF15 was elevated in Juvenile Dermatomyositis and correlated with disease severity." (PMID 40019842, 2025).
fibrosarcoma (2 papers, 2022 to 2024). A malignant mesenchymal fibroblastic neoplasm affecting the soft tissue and bone. "In a study of fibrosarcoma-bearing mice, inhibition of GDF15 function was reported to reverse lipid oxidation and prevent cachexia, posing a currently unexplored association of SASPs such as GDF15 in mediating membrane lipid oxidation in CRC." (PMID 35954376, 2022).
focal segmental glomerulosclerosis (2 papers, 2020 to 2024). A renal disorder characterized by sclerotic lesions in the glomeruli. "In mice, it is involved in podocyte pathogenesis, and in humans, GDF15 is upregulated in the glomeruli of patients with focal segmental glomerulosclerosis." (PMID 32375259, 2020). "In patients with focal segmental glomerulosclerosis (FSGS), GDF15 is significantly upregulated, suggesting a crucial role for GDF15 in the pathogenesis of podocytopathies." (PMID 38607075, 2024).
glomerular disease (2 papers, 2020 to 2025). "To avoid this issue, we used mice deficient in the GDF15 protein, which consistently proves the immunomodulatory functions of GDF15 in glomerular disease." (PMID 32977372, 2020). "Although GDF15 has been shown to affect aspects of chronic diseases (both inflammation and fibrosis), whether it controls glomerular disease progression is unclear." (PMID 32977372, 2020).
glucocorticoid deficiency (2 papers, 2020 to 2026). "Given the site of action of GDF15 in the hindbrain and its effects on appetite, further study is required to determine the effect of GDF15 in mediating the anorexia and nausea that is a common feature of glucocorticoid deficiency." (PMID 31853550, 2020). "Anorexia, weight loss, nausea and vomiting are common manifestations of glucocorticoid deficiency, and we hypothesized that glucocorticoid deficiency may be associated with elevated levels of GDF15." (PMID 31853550, 2020). "To explore this, we measured circulating GDF15 in volunteers with PAI and pharmacologically induced glucocorticoid deficiency and determined its response to glucocorticoid replacement." (PMID 31853550, 2020). "To date, there are no reports on the effect of glucocorticoid deficiency on circulating GDF15." (PMID 31853550, 2020).
gout (2 papers, 2025 to 2026). A condition characterized by painful swelling of the joints, which is caused by deposition of urate crystals. "Collectively, these findings underscore the robust and consistent diagnostic potential of GDF-15 across different phases of gout." (PMID 40722837, 2025). "ROC curve analyses revealed that serum GDF-15 had excellent diagnostic accuracy in discriminating between patients with acute gout attacks and healthy controls, yielding an area under the curve (AUC) of 0.980 (95% CI: 0.945–1.000, p < 0.0001)." (PMID 40722837, 2025). "ROC analysis revealed that GDF-15 exhibits high diagnostic accuracy in distinguishing gout patients from healthy controls; however, its limited ability to differentiate between acute attacks suggests that it should be used in conjunction with other clinical and laboratory markers." (PMID 40722837, 2025). "Further longitudinal and experimental studies are warranted to determine whether GDF-15 plays a causal role in preserving renal function in the context of gout-related systemic inflammation." (PMID 40722837, 2025). "Given that monosodium urate crystals drive gouty inflammation primarily through NLRP3 inflammasome activation and the subsequent release of IL-1β and IL-18, the suppressive effects of GDF15 on these mediators suggest a potential regulatory role in modulating gout-associated inflammatory responses." (PMID 40722837, 2025). "The correlations between GDF-15 and clinical, biochemical, and hematological parameters were assessed separately in the acute gout attack and intercritical gout groups." (PMID 40722837, 2025). "Our findings reveal a significant link between GDF-15 levels and indicators of kidney function in patients with gouty arthritis." (PMID 40722837, 2025). "For intercritical gout, ROC analysis similarly indicated excellent discriminative ability for serum GDF-15 (AUC = 0.966, 95% CI: 0.912–1.020, p < 0.0001)." (PMID 40722837, 2025). "For distinguishing intercritical gout patients, the optimal GDF-15 threshold was 1147.5 pg/mL, achieving sensitivity and specificity values of 93.3%." (PMID 40722837, 2025). "Furthermore, the acute gout attack group showed significantly higher GDF-15 concentrations than the intercritical gout group (p < 0.01)." (PMID 40722837, 2025). "Therefore, this study aimed to determine serum GDF-15 levels in gouty arthritis and to evaluate the relationship between kidney function and GDF-15." (PMID 40722837, 2025). "In the intercritical gout group, GDF-15 was moderately and negatively correlated with eGFR (r = −0.53, p < 0.01), weakly and negatively correlated with albumin (r = −0.37, p < 0.05), and weakly and positively correlated with HDL cholesterol (r = 0.40, p < 0.05)." (PMID 40722837, 2025). "GDF-15 may be a helpful biomarker reflecting disease activity and renal involvement in gouty arthritis." (PMID 40722837, 2025). "Therefore, GDF-15 is a potential biomarker for assessing renal involvement in patients with gout." (PMID 40722837, 2025).
hemochromatosis (2 papers, 2010 to 2017). A disorder of iron metabolism characterized by a triad of HEMOSIDEROSIS; LIVER CIRRHOSIS; and DIABETES MELLITUS. "Genes related to iron regulation, included Hfe, Slc40a1, Hmox1, Tfrc and Gdf15, all of which are directly involved in hemochromatosis and iron overload." (PMID 29257745, 2017). "Very high levels of serum GDF15 were also observed in patients with congenital dyserythropoietic anemia type 1 (CDA I) suggesting that GDF15 contributes to the inappropriate suppression of hepcidin with subsequent secondary hemochromatosis in these patients." (PMID 20827391, 2010).